KRT80 (keratin 80)
Diseases named in the same sentence as KRT80 in open-access papers (continued):
Sharing a sentence is not in itself a finding about the gene and the disease.
tumor (continued). "A947 treatment led to more than a 95% decrease in tumor SMARCA2 protein levels in both models, however a slightly stronger suppression of KRT80 transcript was observed in the HCC515 model." (PMID 36357397, 2022). "For illustrating the contribution of KRT80 in the evolution of NSCLC tumors, we constructed a mouse Xenograft tumor model." (PMID 36248424, 2022). "Notable genes include KRT80 and CDH5 25, 26, which are suspected to function as tumor promoters in human cancers and are highly expressed in PDAC." (PMID 33390837, 2021). "Cytokeratin 80 (KRT80) is a protein type belonging to the keratin family, which has been correlated with more aggressive tumor phenotypes, higher rates of proliferation, enhanced migratory and invasive capabilities, and poorer clinical outcomes in different cancers." (PMID 40647481, 2025). "Overexpression of KRT80 upregulated the expression of cytoskeleton‐related genes, such as SEPT9, and downregulated several genes that play central roles in cancer biology, such as negative regulators of migration and tumor suppressors." (PMID 37211956, 2023). "Moreover, overexpression of HNSCAT1 significantly inhibited tumor progression through HNSCAT1 interaction with miR-1254 and rescued KRT80 expression." (PMID 35965679, 2022). "Analysis of data from the online site UALCAN revealed that KRT80 was dramatically more abundant in primary tumor tissues of lung cell squamous and adenocarcinoma than in normal samples." (PMID 36248424, 2022). "Moreover, some of the candidate genes, such as TRIB3, KRT80, and FAM135B, were found to be correlated with tumor stage or survival outcomes, implying that these candidate genes could serve as promising prognostic biomarkers for COAD patients." (PMID 35610288, 2022). "To compare and validate these data, we assessed KRT80 mRNA and protein expression in paired CRC and non-tumor tissues from CRC patients collected at our hospital, highlighting a critical overexpression in the tumor portions." (PMID 40647481, 2025).
cancer (20 papers, 2018 to 2025). A tumor composed of atypical neoplastic, often pleomorphic cells that invade other tissues. "We revealed a new cancer-promoting mechanism associated with KRT80." (PMID 34659572, 2021). "KRT80 has been rarely reported to be associated with any disease, including cancer." (PMID 30262880, 2018). "In the last few years, KRT80 activity has been investigated due to its peculiar features related to cancer mechanisms and patient outcomes." (PMID 40647481, 2025). "Many studies have investigated the role of KRT80 in tumors, focusing on its regulatory functions in several networks that have an impact on cancer cell mechanisms and on patient outcomes." (PMID 40647481, 2025). "To screen the key genes, we analyzed them using the GSCA database, which showed that high expression of KRT80 and C1QTNF6 in cancer tissues was significantly associated with the overall survival of the samples." (PMID 39247607, 2024). "KRT80 has been shown to be highly expressed in a variety of cancers, including ESCC, GC, CRC, NSCLC, OC, and endocrine‐resistant BC." (PMID 37211956, 2023). "Based on the laboratory findings in existing studies, it is likely that KRT80 plays an important role in the clinical prognosis of these cancers." (PMID 37211956, 2023). "Other important genes in this list downregulated by TOX2-shRNA, such as ITGB7, SLAMF1, CD244, DPYSL3, KRT80 and KRT7, have been implicated in cancer progression or drug resistance." (PMID 37032358, 2023). "We found that PI3K/AKT and MEK/ERK are likely to be the major downstream signaling pathways of KRT80, but it has multiple upstream regulators in different cancers." (PMID 37211956, 2023). "The mechanisms of the roles KRT80 plays in cancer have been partially elucidated, but the molecular mechanisms underlying these processes need to be further clarified." (PMID 37211956, 2023). "All these studies suggest that KRT80 has great research potential in cancer and is likely to be a new cancer marker and therapeutic target." (PMID 37211956, 2023). "The clinical studies will help us to better understand the great potential of KRT80 as a cancer biomarker and therapeutic target, and provide new ideas for cancer diagnosis and treatment." (PMID 37211956, 2023). "Existing studies have shown that KRT80 is significantly more highly expressed in a variety of cancer cells than in normal tissues, promotes cancer cell proliferation, invasion and metastasis, and is associated with poorer prognosis in cancer patients." (PMID 37211956, 2023). "The mechanisms of KRT80 functions in cancer have been partially elucidated, suggesting that KRT80 is a potentially useful cancer therapeutic target." (PMID 37211956, 2023). "In the analysis using surgical specimens (27 paired normal and cancerous tissues), we observed marked suppression of miR-139-3p and marked upregulation of KRT80 in cancer tissues." (PMID 36232922, 2022). "Of these, we focused on KRT80 because its expression was significantly different between cancer and normal tissues." (PMID 36232922, 2022). "We showed that aberrant expression of KRT80 enhanced the malignant phenotypes of cancer cells (i.e., proliferation, migration, and invasion)." (PMID 36232922, 2022). "A knockdown assay using small interfering RNA (siRNA) targeting KRT80 showed that reducing KRT80 expression suppressed the malignant transformation (cancer cell migration and invasion) of CRC cells." (PMID 36232922, 2022). "According to the data in the Oncomine database, KRT80 is overexpressed in many different cancer tissues." (PMID 34659572, 2021). "Amongst them, we found particularly striking the strong KRT80-dependent induction of cortactin (CTTN), a factor directly linked to actin rearrangements, lamellipodia formation and cancer cell invasion, that we confirmed by immunofluorescence." (PMID 31073170, 2019).
cancer (continued). "Our data strongly suggest that therapy plays a direct role in shaping the biophysical properties and invasive potential of cancer cells, by inducing epigenetic rearrangements leading to KRT80 upregulation and concomitant cytoskeletal reorganization." (PMID 31073170, 2019). "We also describe an unexpected role for intermediate filaments in promoting cancer cell invasion by showing for the first time that KRT80 promotes actin cytoskeleton rearrangements." (PMID 31073170, 2019). "KRT80 protein staining was higher in the primary cancer samples as compared with adjacent normal mucosa." (PMID 30262880, 2018). "To investigate whether these processes play a role in KRT80's cancer-promoting function, we analyzed the correlation between KRT80 and 21 methylases and 10 cuproptosis-related genes." (PMID 38495507, 2024). "The differential prognostic significance of KRT80 mRNA expression might be attributable the difference in the treatment approach and efficacy of the cancer patients with different stages, and different infiltration of immune cells." (PMID 38241178, 2024). "The potential marker KRT80 may play an important role in the cancer cell function and the prognosis of cancer patients." (PMID 39247607, 2024). "Interfering with KRT80 expression can influence the cancer-promoting effects driven by VCP." (PMID 38495507, 2024). "Additionally, inhibiting KRT80 can partially counter the cancer-promoting effects of VCP in LUAD and its downstream pathway PI3K." (PMID 38495507, 2024). "The higher level of KRT80 methylation was observed in normal tissue than cancer (p < .05)." (PMID 38241178, 2024). "GC has contributed to much of the research on KRT80 in cancer." (PMID 37211956, 2023). "However, their studies should be extended to more cancers to find common regulators and signaling pathways of KRT80 in different cancers." (PMID 37211956, 2023). "As in GC and CRC, there may be more than one pathway in which KRT80 plays a role in OC, and given its specificity, it is of interest to explore the relationship between the MEK/ERK pathway and KRT80 in cancer." (PMID 37211956, 2023). "Furthermore, KRT80 has been shown to play an important role in the proliferation, migration and invasiveness of several types of cancer cells, including ESCC, GC, CRC, BC and OC, and to promote the adhesion of BC." (PMID 37211956, 2023). "KRT80 can effectively enhance the proliferation, invasiveness and migration of cancer cells." (PMID 37211956, 2023). "Overexpression of KRT80 protein was detected in cancer lesions." (PMID 36232922, 2022). "To date, there have been few studies on KRT80 expression in malignant tumors." (PMID 34659572, 2021). "KRT80 upregulation directly promotes cytoskeletal rearrangements at the leading edge, increased focal adhesion and cellular stiffening, collectively promoting cancer cell invasion." (PMID 31073170, 2019). "Activation of cell type specific enhancers has been linked with cancer transcriptional aberration, leading us to hypothesize that de novo enhancer activation within the TAD structure might control KRT80 expression in AI resistant cells." (PMID 31073170, 2019). "Little is known about the function of Keratin 80 (KRT80), an epithelial keratin, in cancer." (PMID 30262880, 2018). "This is the first report on the function of KRT80 in malignant tumors." (PMID 30262880, 2018). "KRT80 has been observed to interact with PRKDC, activating the AKT signaling pathway and promoting cancer progression." (PMID 38495507, 2024). "Analysis of KRT80 expression across various tumors using the TIMER2 database, revealed differential expression in 18 cancers compared to adjacent normal tissue among 22 tumors." (PMID 38495507, 2024). "Several KRT genes, including the phylogenetically older KRT8, KRT18, KRT19, KRT23, KRT79, KRT80 and KRT222, were found to be differentially expressed in diverse types of cancers." (PMID 36949761, 2023).
cancer (continued). "Several members of the KRT gene family, including the evolutionarily older KRT8, KRT18, KRT19, KRT23, KRT79, KRT80 and KRT222, were shown to be differentially regulated in diverse cancer types." (PMID 36949761, 2023). "Here, the authors find that when aromatase inhibitor treatment resistance develops, epigenomic reprogramming drives Keratin-80 upregulation via SREBP1, and promotes cytoskeletal rearrangements that drive cancer cell invasion." (PMID 31073170, 2019). "The positive rates of KRT80 expression were 85.4% (252/295) and 87.2% (285/327) in esophageal normal tissues and cancers with no statistical significance (p > .05)." (PMID 38241178, 2024). "To investigate whether KRT80 expression could be aberrant in patients affected by CRC we evaluated its levels using UALCAN, an online tool that analyzes the cancer OMICS data from The Cancer Genome Atlas (TCGA) and the Clinical Proteomic Tumor Analysis Consortium (CPTAC)." (PMID 40647481, 2025). "However, the correlation between KRT80 expression and cancer has not been reported, not to mention in CRC." (PMID 30262880, 2018).
KRT80 also shares sentences with these, for which no sentence is quoted: melanoma (3 papers); adenocarcinoma (2); head and neck squamous cell carcinoma (2); infection (2); alveolar rhabdomyosarcoma (1); Bartter syndrome (1); cecum cancer (1); cholangiocarcinoma (1); cutaneous leishmaniasis (1); Ewing sarcoma (1); gastrointestinal tumors (1); leishmaniasis (1); lung squamous cell carcinoma (1); Lymphatic Metastasis (1); non-small cell lung carcinoma (1).